ICAM1 (intercellular adhesion molecule 1)
Diseases named in the same sentence as ICAM1 in open-access papers (continued):
Sharing a sentence is not in itself a finding about the gene and the disease.
atherosclerosis (continued). "Moreover, the aberrant expression of ICAM-1 is associated with other inflammatory diseases such as atherosclerosis, arthritis and cancer." (PMID 32426811, 2020). "Moreover, depletion of PKN3 was shown to attenuate pro-inflammatory activation of endothelial cells caused by defects in glycosylation of ICAM-1 adhesion molecules, suggesting its potential involvement in the promotion of atherosclerosis." (PMID 33092266, 2020). "ICAM-1 is a ligand for lymphocyte function-associated antigen 1 and integrinβ-2, making it an important player in various inflammatory/immune conditions, including atherosclerosis." (PMID 30674642, 2019). "Paricalcitol treatment for 12 weeks to CKD patients in stage 3–4 induces a decline relative to placebo in concentrations of ICAM-1 positive MPs, where soluble ICAM-1 is a marker known to be implicated in atherosclerosis and to correlate with risk of future cardiovascular events." (PMID 31370809, 2019). "ICAM-1 is induced by cytokines and various stress stimuli such as hypoxia, and is associated with a variety of inflammatory diseases and conditions, including atherosclerosis and ischemia reperfusion injury." (PMID 25009606, 2014). "The risk factors for atherosclerosis, such as hypertension, hyperlipidemia and low-density lipoprotein, are associated with the level of adhesion molecules, and ICAM-1 maybe considered as a prognostic factor for atherosclerosis." (PMID 25310099, 2014). "It is noteworthy that studies on the influence of ICAM-1 deficiency during atherosclerosis in mice similarly found that certain experimental conditions (specifics of the diet, mouse background strain, age of study animals) did not result in significant plaque reductions." (PMID 23372835, 2013). "Reducing ICAM‐1 may have a direct effect on improving the hardening or narrowing of arteries, as its overexpression is associated with increased ROS generation, which promotes endothelial dysfunction, the initial stage of atherosclerosis." (PMID 39055210, 2024). "However, evidence has demonstrated that ICAM-1 deficiency substantially protects against atherosclerosis lesion formation in ApoE−/− mice, indicating a controversial issue, which is the dominate mediator between ICAM-1 and VCAM-1 in modulating atherosclerosis progression." (PMID 32472055, 2020). "Another study found that ICAM-1 levels were elevated in the sera of Chlamydia pneumoniae-seropositive patients, which may underlie the mechanisms linking C. pneumoniae infection and atherosclerosis in vivo." (PMID 31293985, 2019). "Additionally, ICAM-1 deficiency protects against atherosclerosis in mice." (PMID 29643466, 2018). "Thus, the K469E polymorphism of ICAM-1 gene may play an important role in inflammation and atherosclerosis." (PMID 23922864, 2013). "Studies have shown that changes in shear stress can activate endothelial inflammation and increase the expression of cell adhesion molecules like VCAM-1 and ICAM-1, promoting atherosclerosis development." (PMID 40416982, 2025). "ICAM-1 overexpression in cellular senescence and its connection to atherosclerosis have been thoroughly examined." (PMID 41470139, 2025). "Upregulation of cellular adhesion molecules like VCAM-1 and ICAM-1 has a close relationship with endothelial injury and dysfunction, which is the primitive phase of atherosclerosis." (PMID 40365513, 2025). "Endothelial dysfunction is a major contributor to atherosclerosis, and biomarkers such as intercellular adhesion molecule-1 (ICAM-1) and vascular cell adhesion molecule-1 (VCAM-1) provide insights into vascular inflammation and leukocyte adhesion." (PMID 40217801, 2025). "During atherosclerosis plaque formation, circulatory soluble adhesion molecules (such as soluble intercellular adhesion molecule-1 [sICAM-1] and soluble vascular adhesion molecule-1 [sVCAM-1]) become activated." (PMID 39013196, 2025).
atherosclerosis (continued). "Our findings clearly show that ICAM‐1, as a marker of subclinical atherosclerosis, was directly correlated with 8‐OHdG as a DNA damage marker." (PMID 40739796, 2025). "Our findings indicate that lactate uptake into ECs via MCT1 increases vascular inflammation by upregulating VCAM‐1 and ICAM‐1, thereby contributing to atherosclerosis." (PMID 39949978, 2025). "Elevated levels of ICAM-1 have been observed in patients with atherosclerosis, heart failure, coronary artery disease, and transplant vasculopathy, as it has been measured in various body fluids." (PMID 40860876, 2025). "Endothelial cells are pivotal in atherosclerosis pathogenesis, leading to the increased expression of adhesion molecules such as intercellular adhesion molecule 1 (ICAM-1) and vascular cell adhesion molecule 1 (VCAM-1)." (PMID 40809841, 2025). "There were 52 upregulated genes related to the lipid and atherosclerosis pathway, including ICAM1, a key player in MSCs-mediated immunosuppression." (PMID 41323777, 2025). "Curcumin has been shown to inhibit the expression of pro-inflammatory mediators, such as C-reactive protein (CRP), TNF-α, IL-1β, and intercellular adhesion molecule-1 (ICAM-1), which play crucial roles in the development and progression of atherosclerosis." (PMID 39941147, 2025). "VCAM-1 and ICAM-1 mediate inflammation and promote leukocyte migration during inflammation, playing a crucial role in atherosclerosis as they facilitate the occurrence of cardiac events." (PMID 40002851, 2025). "In several studies, levels of VCAM-1, ICAM-1, and E-selectin have been correlated with inflammatory processes in the endothelium (e.g., overexpression of VCAM-1 and ICAM-1 in the early stages of atherosclerosis)." (PMID 41373705, 2025). "This resulted in lower expression of NF-κB target genes encoding adhesion molecules (VCAM-1, ICAM-1, E-selectin) and chemokines (CX3CL1, MCP-1, RANTES)––molecules that orchestrate endothelial inflammation and leukocyte recruitment in atherosclerosis." (PMID 40871686, 2025). "Elmorsy et al20 found that 150 mg/kg/day N. sativa powder led to remarkable reduction in serum VCAM-1 and ICAM-1 levels in experimentally-induced atherosclerosis rabbits in comparison to the atherosclerosis control arm." (PMID 40365513, 2025). "Pro-inflammatory cytokines, such as TNF-α and IL-1β, contribute to atherosclerosis by inducing the expression of E-selectin, intercellular adhesion molecule 1 (ICAM-1), and vascular cell adhesion molecule 1 (VCAM-1) in endothelial cells." (PMID 41155632, 2025). "HDL can inhibit endothelial cell adhesion molecules, such as the vascular cell adhesion molecule 1 (VCAM-1), the intercellular adhesion molecule-1 (ICAM-1), and E-selectin, that enable monocytes to bind at the sites of developing atherosclerosis." (PMID 39594433, 2024). "ICAM-1 is another up-regulated endothelial adhesion molecule at the site of atherosclerosis; studies have indicated that the levels of soluble ICAM-1 are correlated with the extent of atherosclerosis." (PMID 38982470, 2024). "The role of ICAM-1 in atherosclerosis and cardiovascular disorders has been extensively evaluated and verified." (PMID 39329738, 2024). "Pro-inflammatory mediators that play a crucial role in the progression of atherosclerosis are cytokines and surface adhesion molecules such as interleukin 8 (IL-8) and intracellular adhesion molecule 1 (ICAM-1)." (PMID 38397822, 2024). "Aldosterone and angiotensin II have been found to induce atherosclerosis and hypertension, respectively, via ICAM-1-dependent mechanisms in experimental models." (PMID 39329738, 2024). "At the early stages of the inflammatory process in atherosclerosis, stimulation and local expression of ICAM-1 and VCAM-1 attract leukocyte recruitment and migration to inflammatory areas." (PMID 39457059, 2024). "We analyzed the expression levels of key atherosclerosis-related genes, namely ICAM-1, VCAM-1, iNOS, and LOX-1, to assess the molecular impact of bilirubin." (PMID 38982470, 2024).
atherosclerosis (continued). "Vascular endothelial cells have critical roles in atherosclerosis and after activation, they express adhesion molecules necessary for monocyte rolling and attachment (e.g., E-selectin, ICAM1 and VCAM1)." (PMID 39858417, 2024). "Diabetic patients exhibit increased ROS production in cardiovascular cells, and activation of intercellular adhesion molecule-1 (ICAM-1) accelerates atherosclerosis progression." (PMID 39749314, 2024). "This increase in plasma H2S levels reduced the size of atherosclerotic plaques and levels of ICAM-1 in plasma and the aorta, which improved atherosclerosis." (PMID 39334911, 2024). "Various inflammatory stimuli such as interleukin-6 (IL-6), tumour necrosis factor-alpha (TNF-α) and intercellular adhesion molecule 1 (ICAM-1) play major roles in atherosclerosis." (PMID 39769058, 2024). "The role of ICAM1 extends beyond inflammation and cancer, as it has been extensively investigated in atherosclerosis." (PMID 38907234, 2024). "The relative upregulation of inflammatory processes in the transcriptomics data can most likely be attributed to genes encoding pro-inflammatory proteins such as VCAM1, ICAM1, and SELE, which are shown to be elevated in the initial stages of atherosclerosis." (PMID 39695567, 2024). "In a cohort of patients with atherosclerosis of carotid artery and coronary artery disease, higher levels of E-selectin and ICAM-1 have been found compared to controls." (PMID 38474219, 2024). "One of the earliest steps of atherosclerosis is the recruitment of leukocytes by endothelial cells through the expression of adhesion molecules (such as ICAM-1 and VCAM-1) induced by IL-1β." (PMID 37476160, 2023). "In that way, it is important to mention that serum levels of iCAM-1 have been associated with endothelial dysfunction and other CVD such as myocardial infarction, coronary heart disease, carotid, and some types of atherosclerosis." (PMID 36678328, 2023). "Like the processes seen in atherosclerosis, nicotine upregulates ICAM-1 and VCAM-1, thereby recruiting leukocytes and activating the production of IL-1β by macrophages." (PMID 37476160, 2023). "The endothelial expression of ICAM-1 is increased in atherosclerotic tissue and animal models of atherosclerosis." (PMID 36835296, 2023). "As for ICAM-1, other studies defined the protein’s crucial role in the development of atherosclerosis by participating in the processes of inflammation and apoptosis." (PMID 37361203, 2023). "It would be valuable to replicate these seminal experiments with updated models to solidify understanding of the role of ICAM-1 in atherosclerosis and the progression of cardiovascular disorders." (PMID 37237555, 2023). "We performed co-localization of immunofluorescence staining of CD31 and ICAM-1 or VCAM-1 in the aortic root sections of two stages of atherosclerosis." (PMID 36923537, 2023). "Here, we found that IL-32θA94V mutant attenuated monocyte-endothelial adhesion, a critical early stage in atherosclerosis, by reducing the expression of ICAM-1 and VCAM-1." (PMID 37228610, 2023). "Concurrently, there is also evidence that down-regulation of ICAM-1 expression by neutralizing antibodies can improve atherosclerosis in rodent models." (PMID 36755923, 2023). "For example, atherosclerosis can induce the expression of Vcam-1, Icam-1, Cxcl12, and Cx3cl1 in SMCs, which in turn facilitates binding to monocytes." (PMID 37686377, 2023). "It has been reported that accumulation of ICAM-1, TNF-RII, VCAM-1, and D-dimer in the vessel wall is a hallmark of atherosclerosis and acute coronary syndrome and is mediated by the interaction between adhesion molecules on endothelial and circulating cells." (PMID 37828979, 2023). "Consumption of sesamin (0.5% w/w) reduced the expression of intracellular adhesion molecule 1(ICAM‐1) and intima thickness in atherosclerosis induced by high‐fat diets in apolipoprotein E (apoE)‐deficient mice." (PMID 37457142, 2023).
atherosclerosis (continued). "During inflammation, TNF‐α increases human antigen R (HuR) translocation and its binding to 3′UTR of ICAM‐1 mRNA which boosts the adhesion of white blood and aortic endothelial cells and eventually inflammation and atherosclerosis." (PMID 37457142, 2023). "Elevated levels of the circulating or soluble form of ICAM-1 are observed in various body fluids in patients with atherosclerosis, heart failure, coronary artery disease, and transplant vasculopathy." (PMID 36835296, 2023). "Recently Yan and co-workers developed a microbubble targeting 3 markers (VCAM-1, ICAM-1 and P-selectin) which are the key players in atherosclerosis has given a new dimension to management of atherosclerosis." (PMID 36756211, 2023). "Monocyte-endothelial adhesion mediated by ICAM-1 and VCAM-1 is an important early step in atherosclerosis, which is a major cause of cardiovascular disease." (PMID 37228610, 2023). "A significant elevation in the level of ICAM-1 in obese and obese with atherosclerosis compared with control group (p < 0.001)." (PMID 36407366, 2022). "The trapping of low-density lipoprotein (LDL) in the intima is the first inducer of atherosclerosis, accompanied by abundantly expressed ICAM-1 in the epithelium, which aids the binding of circulating monocytes to the accumulated oxidized LDL (oxLDL)." (PMID 35806463, 2022). "In the inflamed endothelium, the expression level of ICAM-1 is elevated, which facilitates the formation of atherosclerosis." (PMID 36293483, 2022). "Taken together, these results suggest that SRC-3 promotes ICAM-1 expression during atherosclerosis development." (PMID 36263184, 2022). "Senescent ECs can produce more inflammatory factors such as interleukin-1, interleukin-6, interleukin-8, interleukin-15, MCP-1, TNF, and other mediators that promote atherosclerosis and thrombosis, and express cell adhesion molecules such as ICAM-1, and PAI-1." (PMID 35642067, 2022). "The plasma ICAM-1 level is a marker of endothelial activation and vascular inflammation which is correlated with atherosclerosis." (PMID 36290494, 2022). "SRC-3 accelerated atherosclerosis development, at least in part through increasing endothelial adhesion and the transmigration of leukocytes by promoting ICAM-1 expression in endothelial cells via enhancing NF-κB function." (PMID 36263184, 2022). "Expressions of intercellular adhesion molecule-1 (ICAM-1) by ECs and VSMCs are upregulated in vascular aging-related diseases, such as atherosclerosis, myocardial infarction (MI), and stroke." (PMID 35817770, 2022). "CDH13 has also been shown to be elevated in early atherosclerosis, and ICAM‐1 has been found to be crucial for the development of atherosclerosis." (PMID 35439361, 2022). "In the KEGG signaling pathway analysis of DEGs, we found that RES was associated with fluid shear stress and atherosclerosis, including VCAM1, ICAM1, PECAM1, and other adhesion molecules closely related to atherosclerosis." (PMID 36364780, 2022). "Collectively, these findings demonstrate that inhibiting SRC-3 ameliorates atherosclerosis development, at least in part through suppressing endothelial activation by decreasing endothelial ICAM-1 expression via reducing NF-κB signaling." (PMID 36263184, 2022). "Mechanistically, SRC-3 promoted atherosclerosis development by increasing ICAM-1 expression at the transcriptional level by enhancement of NF-κB function in endothelial cells to promote macrophage recruitment." (PMID 36263184, 2022). "TLR4 accelerates the progression of atherosclerosis and increases the expression of ICAM-1 and VCAM-1, leading to the synergistic activation of NF-κB in vascular walls in vivo and vascular smooth muscle cells in vitro." (PMID 35734399, 2022).
atherosclerosis (continued). "In atherosclerosis, elevated expression of ICAM-1, VCAM-1, and selectins are essential markers of endothelial dysfunction." (PMID 36145277, 2022). "Although researchers found a correlation between the ICAM-1 gene and atherosclerosis or CVDs, we don't have sufficient evidence to prove that the polymorphism of the ICAM-1 gene variants correlates with ICM." (PMID 36440000, 2022). "ICAM-1 is involved in atherosclerosis development by regulating the adhesion of inflammatory cells such as monocytes to endothelial cells and their entry into the sub-endothelium." (PMID 36145277, 2022). "In the early stages of atherosclerosis, damaged or inflamed endothelial cells begin to express selective adhesion molecules on their surface, specifically ICAM-1, which binds to various types of white blood cells before transmigration into the intima." (PMID 35215505, 2022). "SRC-3 depletion or pharmacological inhibition of SRC-3 by bufalin ameliorated atherosclerosis development, at least in part by decreasing endothelial ICAM-1 expression via reduction of NF-κB function." (PMID 36263184, 2022). "Initiation of atherosclerosis begins with aberrant endothelial cells coupled with augmented expression of surface adhesion molecules such as intercellular adhesion molecule 1 (ICAM-1), vascular cell adhesion molecule 1 (VCAM-1), and E-selectin." (PMID 36361845, 2022). "Regulation of CAM proteins VCAM-1 and ICAM-1 will require a critical strategy to prevent and regulate chronic inflammatory disorders including atherosclerosis." (PMID 35788200, 2022). "V55 diminished the expression of Icam-1, Egfr, Wnt5a and Mmp7 (related to inflammation and tissue damage in periodontal disease) and Scd1, Scd2, Egf1 (related to atherosclerosis)." (PMID 35631379, 2022). "RNA-Seq and Western blot analyses of the aorta revealed that SRC-3 was required for maintaining the expression of ICAM-1, which was required for macrophage recruitment and atherosclerosis development." (PMID 36263184, 2022). "ICAM-1 expression is elevated in atherosclerosis-prone aortas and is regulated by proinflammatory stimuli." (PMID 36358491, 2022). "The cellular adhesion molecules (CAM), such as vascular cell adhesion molecule-1 (VCAM-1) and intracellular adhesion molecule-1 (ICAM-1) in blood vessels have a critical role in the progression of lesions in atherosclerosis." (PMID 35788200, 2022). "This process is accompanied by upregulation of vascular cell adhesion molecule-1 (VCAM-1) and intercellular adhesion molecule-1 (ICAM-1), and oxidized lipids and adhesion molecules mutually promote the plaque formation process of atherosclerosis." (PMID 36133804, 2022). "ICAM-1 is proven to be a molecular marker for atherosclerosis and the development of coronary heart disease." (PMID 34191823, 2021). "Both the atherosclerosis markers ie mean ICAM-1 and Lp(a) were significantly higher in the NAFLD group compared to the non-NAFLD group (334.53±72.86 vs 265.46 ±102.92 ng/mL, p = 0.001, 85.41±52.56 vs 23.55±23.66 nmol/L, p <0.001, respectively)." (PMID 34191823, 2021). "The levels of biomarkers of endothelial dysfunction and atherosclerosis, such as intercellular adhesion molecule-1 (ICAM-1) and vascular cell adhesion molecule-1 (VCAM-1), are increased in the serum of patients receiving hemodialysis." (PMID 34769353, 2021). "Endothelial dysfunction is considered an early indicator of atherosclerosis and is characterized by the overexpression of adhesion molecules, including intercellular adhesion molecule-1 (ICAM-1) and vascular cell adhesion molecule-1 (VCAM-1)." (PMID 34320932, 2021). "Genetic deletion of SGEF resulted in decreased atherosclerosis by reducing docking structure formation (enriched with ICAM-1) and monocyte infiltration." (PMID 33804952, 2021).